IFNK (interferon kappa)
Description:
May play a role in the regulation of immune cell function. Cytokine that imparts cellular protection against viral infection in a species-specific manner. Activates the interferon-stimulated response element signaling pathway. It is able to directly modulate cytokine release from monocytes and dendritic cells. Binds heparin.
Synonyms: IFNT1; INFE1
Tractability: Antibody: UniProt places it where antibodies can reach, with medium confidence; UniProt predicts a signal peptide or a membrane-spanning region; its Gene Ontology location is reachable by antibodies, with medium confidence.
Gene: Protein-coding gene on chromosome 9 (27,524,290 to 27,526,498, forward strand). Ensembl gene ENSG00000147896.
Subcellular location: Secreted
Gene Ontology:
Molecular function: type I interferon receptor binding; cytokine activity; cytokine receptor binding
Biological process: cytokine-mediated signaling pathway; regulation of DNA-templated transcription; response to virus; adaptive immune response; B cell activation involved in immune response; cellular response to virus; humoral immune response; natural killer cell activation; natural killer cell activation involved in immune response; negative regulation of cell population proliferation; positive regulation of innate immune response; response to exogenous dsRNA; T cell activation involved in immune response; type I interferon-mediated signaling pathway; defense response
Cellular component: extracellular region
Genetic constraint (gnomAD): Loss-of-function variants: 13 observed, 12.4 expected, observed/expected ratio (o/e) 1.05, 90% interval 0.68 to 1.64. The upper end of that interval is the gene's LOEUF score, 1.64, which puts it in group 6 of 6, group 1 being the genes least tolerant of losing a copy. Missense variants: 248 observed, 249.42 expected, observed/expected ratio (o/e) 0.99, 90% interval 0.9 to 1.11. Synonymous variants: 94 observed, 87.73 expected, observed/expected ratio (o/e) 1.07, 90% interval 0.91 to 1.27.
Homologues: Orthologues: chimpanzee IFNK (98% identical), macaque IFNK (94% identical), dog IFNK (72% identical), pig IFNK (68% identical), rabbit IFNK (56% identical), rat Ifnk (35% identical), mouse Ifnk (34% identical), zebrafish ifnphi3 (21% identical), zebrafish ifnphi2 (19% identical), tropical clawed frog ifn4 (18% identical). Paralogues in human: IFNA14 (31% identical), IFNA16 (30% identical), IFNA17 (30% identical), IFNA5 (30% identical), IFNA1 (29% identical), IFNA13 (29% identical), IFNW1 (29% identical), IFNA10 (29% identical), IFNA6 (29% identical), IFNA8 (29% identical), IFNA2 (29% identical), IFNA4 (29% identical), and 4 more.
Diseases named in the same sentence as IFNK in open-access papers:
IFNK is named in the same sentence as 28 diseases in open-access papers, as found by Europe PMC text mining. Sharing a sentence is not in itself a finding about the gene and the disease. The quoted sentences say what the papers report.
lupus (14 papers, 2014 to 2025). "Specifically, keratinocytes increase the production of proinflammatory cytokines such as IL-6 in response to IFNκ in lupus and conversely neutralization of IFNκ suppresses their IL-6 production." (PMID 39372419, 2024). "More specifically, keratinocyte specific secretion of IFNκ increases after UVB treatment of lupus keratinocytes and neutralization of this type I IFN abrogates IL-6 production." (PMID 30405625, 2018). "Recent evidence suggests that epidermal signals instruct the immune system in SLE, but whether epidermal IFNκ alone is sufficient to drive lupus phenotypes has not been investigated." (PMID 40776772, 2025).
viral infections (9 papers, 2010 to 2025). "We first picked the interferon-kappa (IFNK) gene as it has been implicated in viral disease (13, –, 15) and previously had been successfully targeted, so we knew that the knockouts would be viable." (PMID 37695101, 2023). "On the opposite strand at the same location is IFNK, which encodes interferon κ precursor, which is important for immunity to viral infection." (PMID 20801717, 2010). "Other important members of the type I IFN family (IFNε, IFNκ) were already characterized during viral infections like HSV-1/2, Zika virus or human papillomavirus (HPV) in the vaginal tract or in HSV-1-infected keratinocytes." (PMID 36325470, 2022). "Keratinocytes express a specific type of IFN known as IFNκ, with κ standing for keratinocyte, that is constitutively expressed at low levels and is upregulated following viral infection." (PMID 34372596, 2021). "Importantly, treatment of HPV-positive cell lines with IFNκ inhibited viral replication and cell growth, further demonstrating the importance of suppressing this interferon upon viral infection." (PMID 34372596, 2021).
cutaneous lupus erythematosus (6 papers, 2017 to 2025). An autoimmune disorder that manifests as different lupus-specific skin disorders; it can occur with systemic lupus erythematosus, or as a singular disease. "Polymorphisms in IFNK (IFN-κ) have been implicated in cutaneous lupus erythematosus and exhibit sex-dependent effects." (PMID 41301504, 2025). "In addition, IFNK expression was reported to be significantly increased in lesional skin of patients with cutaneous lupus erythematosus related to photosensitivity." (PMID 33262343, 2020).
cervical cancer (5 papers, 2012 to 2022). A primary or metastatic malignant neoplasm involving the cervix. "Consistently, HPV16-positive cervical intraepithelial neoplasia and cervical cancer tissues are devoid of IFNκ expression, whereas HPV16-negative normal mucosal tissues display strong IFNκ expression." (PMID 29438328, 2018). "Others have shown that IFNκ is the primary interferon expressed in keratinocytes and that attenuation of IFNκ is seen in both HPV-harboring foreskin keratinocytes and in HPV positive cervical cancer samples compared to non HPV- infected controls." (PMID 29137231, 2017).
diabetes (3 papers, 2017 to 2024). "Overexpression of IFNα or IFNκ in pancreatic β cells of mice not normally prone to T1D leads to onset of diabetes with severe insulitis, hypoinsulinemia, and diabetes." (PMID 28959234, 2017).
psoriasis (3 papers, 2020 to 2024). An autoimmune condition characterized by red, well-delineated plaques with silvery scales that are usually on the extensor surfaces and scalp. "It was shown, that serum IFNκ was elevated in inflamed skin diseases, such as cutaneous lupus and psoriasis." (PMID 39399119, 2024).
breast carcinoma (2 papers, 2018 to 2023). "Survival and Cox analyses of all the DEGs confirmed CCL1 and MYH6 were independent protective factors and IFNK and SOAT2 were independent risk factors for basal-like breast cancer (95%CI: 1.06–2.5, p = 0.026)." (PMID 36694223, 2023). "On the contrary, IFNK, MYH6, and SOAT2 have rarely been reported in association with breast cancer." (PMID 36694223, 2023). "We further constructed a four-gene signature comprising CCL1, IFNK, MYH6, and SOAT2 genes, which shows a promising predictive value for basal-like breast cancer and may be related to the underlying Th1/Th2 balance regulation mechanism, which is worthy of further study." (PMID 36694223, 2023). "CCL1, MYH6, IFNK, and SOAT2 have an independent prognostic value of survival outcome and might be novel markers in basal-like breast cancer." (PMID 36694223, 2023).
polyarticular JIA (1 paper, 2024). "The finding that IFNκ expressions are low in both polyarticular JIA and RA aligns with the concept of shared characteristics between these conditions, potentially informing JIA classification and may be useful in management strategies." (PMID 39399119, 2024).
cancer (5 papers, 2012 to 2021). A tumor composed of atypical neoplastic, often pleomorphic cells that invade other tissues. "The most interesting finding is that TNF-alpha is directly and significantly regulated by IFNK, a gene that has not been previously related with cancer in literature." (PMID 30458775, 2018). "The functional analysis performed to the genetic signature obtained with the Gene-disease approach showed a significant presence of genes related with cancer, as well as one gene (IFNK) and one pseudogene (PCNAP1) which a priori had not been described to be related with cancer." (PMID 30458775, 2018).
infection (5 papers, 2014 to 2025). The state of being infected such as from the introduction of a foreign agent such as serum, vaccine, antigenic substance or organism. "Thus, from the perspective of HSV-1-invading strategy, we speculate that IFNκ is one of the critical targets for the virus to overcome in order to establish effective infection in keratinocytes." (PMID 32352019, 2020).
tumor (4 papers, 2024 to 2025). "Based on previous studies, which already reported that the IFN family members could induce ferroptosis, they demonstrated, using human lung cell lines, that IFNκ can sensitized tumor cells to ferroptosis." (PMID 41339932, 2025).
infectious disease (1 paper, 2018). A disorder directly resulting from the presence and activity of a microbial, viral, or parasitic agent in humans. "The only IPA network containing IFNK corresponds to cell death and survival, infectious diseases, and cellular compromise, where 11 genes forming the network were present in the signature." (PMID 30458775, 2018).
IFNK also shares sentences with these, for which no sentence is quoted: COVID-19 (3 papers); allergic contact dermatitis (2); inflammatory skin disease (2); influenza (2); autoimmune disease (1); cervical intraepithelial neoplasia (1); experimental autoimmune encephalomyelitis (1); lupus erythematosus (1); neuropathy (1); oligoarticular JIA (1); pneumonia (1); pulmonary disease (1); rheumatoid arthritis (1); Sjögren’s Syndrome (1); squamous intraepithelial lesions (1); viral disease (1).